TDRG1 (testis development related 1)
Synonyms: LINC00532; lincRNA-NR_024015
Gene: Long non-coding RNA gene on chromosome 6 (40,285,680 to 40,387,590, forward strand). Ensembl gene ENSG00000204091.
Diseases named in the same sentence as TDRG1 in open-access papers:
TDRG1 is named in the same sentence as 17 diseases in open-access papers, as found by Europe PMC text mining. Sharing a sentence is not in itself a finding about the gene and the disease. The quoted sentences say what the papers report.
seminoma (8 papers, 2018 to 2022). A radiosensitive malignant germ cell tumor found in the testis (especially undescended), and extragonadal sites (anterior mediastinum and pineal gland). "We previously identified testis developmental related gene 1 (TDRG1), a gene implicated in proliferation of TCam‐2 seminoma cells." (PMID 31496041, 2019). "As expected, the level of miRNA‐106b‐5p was negatively associated with TDRG1 expression in seminoma (P < 0.05), while H19 showed a positive correlation with TDRG1 expression (P < 0.05)." (PMID 30430771, 2018). "TDRG1 is upregulated in testicular seminoma tissues and promotes the development, migration, and chemotherapy resistance of seminoma cells." (PMID 36289466, 2022). "In this way, H19 would directly lead to TDRG1 upregulation, leading to seminoma cisplatin resistance." (PMID 33767982, 2021). "TDRG1 peptide action in seminoma mainly relies on the activation of PI3K/Akt/mTOR oncogenic signaling pathway, since it is able to positively regulate the expression levels of p-PI3K, p-Akt, and p-mTOR, as well as to affect the translocation of nuclear p-Akt." (PMID 33767982, 2021). "Testis developmental related gene 1 (TDRG1) induces seminoma cell proliferation and invasion via activation of PI3K/AKT pathway." (PMID 37303943, 2021). "The authors proposed TDRG1, whose expression is exclusive in testis, to influence chemoresistance based on a previous work, which reported TDRG1 affecting resistance to cisplatin treatment in seminoma by regulating the PI3K/Akt/mTOR pathway." (PMID 32756406, 2020). "The data indicated that the expression levels of LC‐3II, an autophagy marker, and TDRG1 were higher in seminoma than in normal tissue, demonstrate a potential relationship between TDRG1 and autophagy in seminoma." (PMID 31496041, 2019). "Expression of TDRG1 and LC3‐II (microtubule‐associated protein 1 light chain 3B) at the protein level of testicular seminoma tissues and normal testicular tissues was detected by Western blot." (PMID 31496041, 2019). "We examined the expression of TDRG1 and the level of autophagy in both normal testicular tissues and seminoma." (PMID 31496041, 2019). "We found that TDRG1 upregulation promoted autophagy in both TCam‐2 cells and seminoma xenografts via p110β/Rab5/Vps34 activation." (PMID 31496041, 2019). "Xenograft tumour model in male BALB/c nude mice was established to investigate the effect of TDRG1 on the chemosensitivity of seminoma cells to CDDP through autophagy in vivo." (PMID 31496041, 2019). "In summary, our findings show that high expression of TDRG1 supports a high level of autophagy in seminoma." (PMID 31496041, 2019). "However, the significant associations between TDRG1 and the two ncRNAs in seminoma, combined with their differential expression between normal and tumor tissues as well as between CDDP‐resistant tumor cells and their origins, may help us to understand their roles in CDDP sensitivity." (PMID 30430771, 2018). "Because TDRG1 can modulate seminoma cell sensitivity to CDDP, as previously reported, we further assessed the impact of miRNA‐106b‐5p on the response of TCam‐2 cells to CDDP." (PMID 30430771, 2018). "Due to the difficult nature of collecting tumor tissues from CDDP‐resistant seminoma patients, it was challenging to directly compare the levels of H19, miRNA‐106b‐5p, and TDRG1 between primary tumors and their CDDP‐resistant counterparts." (PMID 30430771, 2018). "The role of TDRG1 in tumorigenesis and the progression of seminoma, as well as its role in regulating chemosensitivity of seminoma to cisplatin through the PI3K/Akt/mTOR signaling pathway, has been previously defined." (PMID 30430771, 2018). "Combining the previous results, we demonstrated that H19 promoted the expression of TDRG1 by sequestering miRNA‐106b‐5p in seminoma cells." (PMID 30430771, 2018). "The H19/miRNA‐106b‐5p/TDRG1 axis was validated in homeostatic seminoma as well as in a CDDP‐resistant context." (PMID 30430771, 2018).
seminoma (continued). "H19 over-expression increases resistance to bortezomib by targeting miR-29b-39 to increase myeloid cell leukemia 1 (MCL-1) expression in multiple myeloma cells and to cisplatin by targeting miR-106b-5p to enhance testis development-related 1 (TDRG1) expression in seminoma cells." (PMID 32272875, 2020). "Although inhibition of autophagy can enhance chemosensitivity in many kinds of cancers, whether TDRG1 is involved in regulating the chemical sensitivity of CDDP through autophagy in seminoma remains unclear." (PMID 31496041, 2019). "We believe that elucidating the mechanisms enhancing TDRG1 expression in seminoma may help us further understand the progression of this disease and how tumor cells survive under CDDP treatment." (PMID 30430771, 2018). "As TDRG1 can regulate sensitivity of CDDP in seminoma cells, we hypothesized that both H19 and miRNA‐106b‐5p may play important roles in CDDP resistance." (PMID 30430771, 2018). "In fact, TDRG1 peptide was also described to promote seminoma cisplatin chemoresistance inhibiting mitochondria-mediated apoptosis and promoting autophagy, mechanisms which have not been described for TDRG1 lncRNA and which could support a functional relevance of the peptide." (PMID 33767982, 2021). "However, whether TDRG1 protein regulates autophagy in seminoma cells and influences their sensitivity to cis‐dichlorodiammine platinum (CDDP) remains unknown." (PMID 31496041, 2019). "Furthermore, the newly identified H19/miRNA‐106b‐5p/TDRG1 axis may serve as a potential target for the treatment of seminoma and the CDDP‐resistant tumors." (PMID 30430771, 2018). "TDRG1 regulated the CDDP sensitivity through the PI3K/AKT/mTOR signaling and intrinsic apoptosis pathway in seminoma cells." (PMID 37303943, 2021). "This study has uncovered a novel role of TDRG1 in reducing chemoresistance during CDDP treatment and provides potential therapeutic strategies for the treatment of human seminoma." (PMID 31496041, 2019). "This study has uncovered a novel role of TDRG1 in determining chemoresistance during CDDP treatment and provides potential therapeutic strategies for the treatment of human seminoma." (PMID 31496041, 2019). "Down-regulated expression of TDRG1 reduced the biological activity of TGCT cells, and enhanced proliferation and migration of seminoma cells through modulation of the PI3 K/Akt/mTOR signaling pathway and mitochondria-mediated apoptotic pathway." (PMID 31164797, 2019). "Not only did we report that the ncRNAs expression was confirmed, we also found that their interactions regulate the expression of TDRG1 and CDDP sensitivity in seminoma." (PMID 30430771, 2018). "Moreover, we showed that TDRG1 facilitates the invasiveness and proliferation of seminoma cells by activating the PI3K/Akt signalling pathway, meaning that TDRG1 has a carcinogenic role in seminoma." (PMID 31496041, 2019). "Remarkably, lncRNA TDRG1 was described to activate the same pathway in endometrial carcinoma and osteosarcoma, thereby one could argue that PI3K/Akt/mTOR pathway activation in seminoma is also ascribable to this lncRNA." (PMID 33767982, 2021). "In the present study, we investigated the effects of TDRG1 protein on tumour growth in vivo and on autophagy, cell viability, apoptosis and the p110β/Rab5/Vps34 (PI3‐kinase Class III) pathway of seminoma TCam‐2 cells in vitro, with or without CDDP treatment." (PMID 31496041, 2019).
endometrial carcinoma (5 papers, 2019 to 2023). A malignant tumor arising from the epithelium that lines the cavity of the uterine body. "For example, LncRNA TDRG1 directly associates with VEGF protein to increase VEGF protein and promotes the progression of endometrial carcinoma." (PMID 34307380, 2021). "The lncRNA testis developmental related gene 1 (TDRG1) has been identified as a proto-oncogene for many tumor types, including gastric carcinoma, cervical cancer, epithelial ovarian cancer, endometrial cancer, and testicular germ cell tumors." (PMID 34178467, 2021). "Further, as a lncRNA, TDRG1 plays important role in cell proliferation, migration and invasion in epithelial ovarian carcinoma and endometrial carcinoma." (PMID 31164797, 2019). "In addition, overexpression of lncRNA TDRG1 promotes the viability, invasion and migration of endometrial cancer cells, inhibits cell apoptosis, and upregulates the expression of VEGF-A, PI3K, Bcl-2, MMP2 and surviving." (PMID 36338699, 2022). "Furthermore, as a lncRNA, TDRG1 enhanced tumorigenicity by inhibiting the miR-93/RhoC pathway in epithelial ovarian carcinoma and promoted endometrial carcinoma cell development and invasion by positively targeting VEGF-A in endometrial carcinoma." (PMID 31164797, 2019). "Lnc TDRG1: Human testis-specific gene testis development-related gene 1 (TDRG1) is an Lnc-RNA of interest due to its proliferative functions studied in bone marrow and endometrial carcinoma and its connection with VEGF-a." (PMID 37762249, 2023). "With the in-depth research, TDRG1 was considered as a key regulator in reproductive organ related cancer such as testicular germ cell tumors (TGCT), epithelial ovarian carcinoma and endometrial carcinoma." (PMID 31164797, 2019).
cervical cancer (4 papers, 2019 to 2022). A primary or metastatic malignant neoplasm involving the cervix. "TDRG1 promotes hypoxia-induced glycolysis via the miR-214-5p/SEMA4C axis in cervical cancer cells." (PMID 35406713, 2022). "The biological role of TDRG1 in cervical cancer (CC) progression remains largely unknown." (PMID 31164797, 2019). "In addition, TDRG1 activates MAPK1 by sponging miR-326, and TUG1 regulates cervical cancer sensitivity to cisplatin via the MAPK pathway." (PMID 35406713, 2022).
testicular germ cell tumor (3 papers, 2019 to 2022). A germ cell tumor arising from the testis. "lincRNA-NR_024015 (gene ID: 732253), namely TDRG1, was initially identified as a novel human testis-specific gene which served as a regulator in sperm motility and the development of testicular germ cell tumors." (PMID 35910890, 2022). "TDRG1 was initially considered as a key regulator in sperm motility, and was involved in the development and progression of testicular germ cell tumors." (PMID 31164797, 2019).
Hyperglycemia (2 papers, 2019 to 2025). An increased concentration of glucose in the blood. "Consistent with the in vivo results, the mRNA levels of lncRNA TDRG1 and VEGF were enhanced by hyperglycemia in HRECs, with observed increases of 2.0-fold in lncRNA TDRG1 and 2.5-fold in VEGF." (PMID 32082175, 2019). "Moreover, VEGF was repressed following the downregulation of lncRNA TDRG1 in hyperglycemia-induced HRECs." (PMID 32082175, 2019). "Notably, hyperglycemia upregulated the mRNA levels of lncRNA TDRG1 and VEGF, with an increase of more than 1.5-fold in HRECs, but there was no distinct difference between the high-glucose group and the negative transfection group." (PMID 32082175, 2019). "In human retinal microvascular endothelial cells, hyperglycemia induced VEGF expression, while knockdown of TDRG1 reversed this effect." (PMID 40429961, 2025). "Knockdown of lncRNA TDRG1 significantly suppressed the increased expression of lncRNA TDRG1 and VEGF induced by hyperglycemia, resulting in a level close to the normal level." (PMID 32082175, 2019). "Correspondingly, the enhanced protein level of VEGF induced by hyperglycemia was inhibited by separate transfection of lncRNA TDRG1 and VEGF siRNAs, while the negative control transfection resulted in no changes." (PMID 32082175, 2019). "While TDRG1 promotes tumor progression and immune evasion by upregulating VEGF-A levels, thereby potentially contributing to endothelial anergy and impaired immune cell infiltration, MEG3 acts as a tumor suppressor by repressing VEGF expression under stress conditions such as hyperglycemia." (PMID 40429961, 2025).
osteosarcoma (2 papers, 2021 to 2023). A usually aggressive malignant bone-forming mesenchymal neoplasm, predominantly affecting adolescents and young adults. "Testis developmental related gene 1 (TDRG1) is a lncRNA that promotes the tumorigenesis and progression of a number of tumors, among which epithelial ovarian cancer, uterine cancers, gastric carcinoma, NSCLC, and osteosarcoma." (PMID 33767982, 2021).
testicular seminoma (2 papers, 2019 to 2022). A malignant germ cell tumor arising from the testis. "Our previous study demonstrated that it encodes a 100‐amino acid protein (TDRG1 protein) whose expression is enhanced in testicular seminoma than in normal testis." (PMID 31496041, 2019). "In testicular seminoma tissues, the TDRG1/GAPDH ratio increased to 0.23 ± 0.02 (P < .001) and the LC3‐II/GAPDH ratio increased to 0.18 ± 0.01 (P < .001)." (PMID 31496041, 2019).
cervical tumor (1 paper, 2019). "The results showed that TDRG1 expressions were increased in cervical tumor tissues compared with normal tissues (P < 0.001)." (PMID 31164797, 2019).
lymph node metastasis (1 paper, 2019). "The elevated expressed TDRG1 was positively correlated with advanced stage (IIb-IIIa), lymph node metastasis (Yes) and depth of cervical invasion (≥ 2/3) in patients (P < 0.001)." (PMID 31164797, 2019). "In addition, the correlation between TDRG1 expression and clinicopathological characteristics (including FIGO stage, lymph node metastasis and depth of cervical invasion) of CC patients were analyzed." (PMID 31164797, 2019).
Obesity (1 paper, 2016). Accumulation of substantial excess body fat. "We observe significant associations of adiposity-OTU abundances with host genetic variants in the FHIT, TDRG1 and ELAVL4 genes, suggesting a potential role for host genes to mediate the link between the fecal microbiome and obesity." (PMID 27666579, 2016).
tumor (8 papers, 2018 to 2025). "LincRNA-NR_024015, also known as Testis development related gene 1 (TDRG1), is a newly identified tumor-associated lncRNA." (PMID 35910890, 2022). "TDRG1 knockdown inhibited tumour growth and promoted apoptosis in TCam‐2 cell xenografts, whereas TDRG1 overexpression had the opposite effect." (PMID 31496041, 2019). "After four cycles of CDDP(IC25) treatment, the mean volume of tumours with TDRG1 overexpression was significantly bigger and TDRG1 knockdown or 3‐MA treatment obviously smaller than control." (PMID 31496041, 2019). "The tumor growth and tumor size in shRNA TDRG1 group were markedly slower and smaller than shNC group (P < 0.001)." (PMID 31164797, 2019). "After 5 weeks, the tumor weight was dramatically reduced in shRNA TDRG1 treated group compared with shNC group (P < 0.001)." (PMID 31164797, 2019). "Multiple lncRNAs regulate VEGF expression in tumor cells under various conditions, including Testis Development-Related Gene 1 (TDRG1), MEG3, H19, SNHG1, Non-Coding RNA Activated by DNA Damage (NORAD), Antisense Non-Coding RNA in the INK4 locus (ANRIL), and MALAT1." (PMID 40429961, 2025). "Similarly, the expression of TDRG1 was highly expressed in cancerous tissues and acted as an oncogene to activate tumor cells proliferation and invasion in above productive organ related cancer." (PMID 31164797, 2019). "In other words, miR-326 acts as a tumor suppressor in TDRG1 regulation of tumorigenicity in CC." (PMID 31164797, 2019). "Xenograft tumour model was established to determine the role of TDRG1 in vivo." (PMID 31164797, 2019). "Studies have shown that lncRNA TDRG1 could serve as a proto-oncogene in multiple tumor types." (PMID 35910890, 2022). "In the context of cancer, the frequent downregulation of MEG3 and overexpression of TDRG1 may synergistically enhance VEGF-driven vascular remodeling, facilitating immune escape and tumor dissemination." (PMID 40429961, 2025). "Tumor suppressive lncRNAs (GAS5, MEG3, FER1L4 and LINC00672) and oncogenic lncRNAs (CCAT2, BANCR, NEAT1, MALAT1, H19, Linc-RoR, TUG1, TDRG1 and PCGEM1) may be a few such examples." (PMID 30781521, 2019).
cancer (6 papers, 2019 to 2021). A tumor composed of atypical neoplastic, often pleomorphic cells that invade other tissues. "These seven lncRNA, including SNHG17, WAC-AS1, LINC00623, SSBP3-AS1, and TDRG1, are yet to tested experimentally for their association and role in ES, although some have functional roles in other cancers." (PMID 34440137, 2021). "In lung cancer cells, TDRG1 enhances the migration, metastasis, and malignancy of cancer cells by promoting ZEB1 expression through miR-873-5p down-regulation." (PMID 32664703, 2020). "Recently, lncRNA-Testis developmental related gene 1 (TDRG1) was proved to be a key modulator in reproductive organ-related cancers." (PMID 31164797, 2019). "In present study, we firstly found that lncRNA TDRG1 was highly expressed in CC patients’ tissues and CC cell lines compared with normal tissue and non-cancer cells." (PMID 31164797, 2019). "LncRNA TDRG1 was studied in vascularity in cancers and shown to modulate VEGF-α to aggravate the dysfunction of cancer cells, which is also a key step in the angiogenesis of DR, indicating the possible involvement of lncRNA TDRG1 in DR." (PMID 32082175, 2019). "Conversely, lncRNA TDRG1 is an oncogenic factor that is able to regulate miRs in cancer cells." (PMID 32664703, 2020). "Based on these findings, TDRG1 has been considered as a critical modulator in several reproductive organ-related cancers, however, the role and potential mechanism of TDRG1 in the tumorigenesis and progression of CC has not been fully investigated." (PMID 31164797, 2019). "During cancer treatment, the PI3K/Akt signaling pathway is often targeted to inhibit cancer cell proliferation; for example, the signaling pathway is controlled by the inhibition of lncRNA TDRG1 expression in osteosarcoma cells, thus interfering with their proliferation." (PMID 34916492, 2021).
TDRG1 also shares sentences with these, for which no sentence is quoted: diabetic retinopathy (2 papers); gastric carcinoma (1); melanoma (1); multiple myeloma (1); Myocardial fibrosis (1).